QSOX2 (quiescin sulfhydryl oxidase 2)
Description:
Sulfhydryl oxidase that catalyzes the oxidation of protein thiol groups to form disulfide bonds, with the reduction of oxygen to hydrogen peroxide (By similarity). May contribute to disulfide bond formation in secreted proteins (By similarity). May play a role in regulating the sensitization of neuroblastoma cells for interferon-gamma-induced apoptosis. Required for normal ovarian function (By similarity).
Synonyms: QSCN6L1; SOXN; DKFZp762A2013
Tractability: Antibody: UniProt places it where antibodies can reach, with high confidence; UniProt predicts a signal peptide or a membrane-spanning region; its Gene Ontology location is reachable by antibodies, with medium confidence. PROTAC: ubiquitination databases record sites on it; its protein half-life has been measured.
Gene: Protein-coding gene on chromosome 9 (136,206,333 to 136,245,812, reverse strand). Ensembl gene ENSG00000165661.
Subcellular location: Membrane; Secreted; Cell membrane; Nucleus membrane
Subcellular location (Human Protein Atlas): Golgi apparatus; Nucleoplasm
Gene Ontology:
Molecular function: flavin-dependent sulfhydryl oxidase activity; protein disulfide isomerase activity; thiol oxidase activity
Biological process: female gonad development; protein folding
Cellular component: Golgi apparatus; nucleoplasm; Golgi membrane; extracellular region; membrane; nuclear membrane; plasma membrane
Genetic constraint (gnomAD): Loss-of-function variants: 45 observed, 58.22 expected, observed/expected ratio (o/e) 0.77, 90% interval 0.61 to 0.99. The upper end of that interval is the gene's LOEUF score, 0.99, which puts it in group 4 of 6, group 1 being the genes least tolerant of losing a copy. Missense variants: 801 observed, 850.99 expected, observed/expected ratio (o/e) 0.94, 90% interval 0.89 to 1. Synonymous variants: 349 observed, 346.43 expected, observed/expected ratio (o/e) 1.01, 90% interval 0.92 to 1.1.
Homologues: Orthologues: chimpanzee QSOX2 (99% identical), macaque QSOX2 (95% identical), rat Qsox2 (79% identical), dog QSOX2 (78% identical), guinea pig QSOX2 (77% identical), pig QSOX2 (75% identical), mouse Qsox2 (69% identical), zebrafish qsox2 (53% identical), tropical clawed frog qsox2 (50% identical), Drosophila melanogaster Qsox1 (24% identical), Drosophila melanogaster Qsox2 (24% identical), Caenorhabditis elegans T10H10.2 (23% identical), and 2 more. Paralogues in human: QSOX1 (37% identical).
Diseases named in the same sentence as QSOX2 in open-access papers:
QSOX2 is named in the same sentence as 20 diseases in open-access papers, as found by Europe PMC text mining. Sharing a sentence is not in itself a finding about the gene and the disease. The quoted sentences say what the papers report.
neuroblastoma (4 papers, 2008 to 2025). Neuroblastoma (NB) is the most common solid, extracranial childhood tumor. "Interestingly, despite an early identification (from human neuroblastoma cells) of QSOX2 protein and its associated gene, up to date, limited information is available on QSOX2 protein." (PMID 28662655, 2017). "QSOX2 was found to regulate the sensitivity of neuroblastoma cells to interferon-gamma-induced apoptosis, also suggesting a role in immune regulation in GBM." (PMID 41226720, 2025). "In neuroblastoma, QSOX2 is a major player in regulating the sensitivity of neuroblastoma cells to IFN-γ-induced apoptosis." (PMID 34350181, 2021). "However, only one published report has found that the overexpression of QSOX2 increases the sensitivity of neuroblastoma cells to proapoptotic stimuli." (PMID 34350181, 2021).
colorectal cancer (3 papers, 2021 to 2025). A primary or metastatic malignant neoplasm that affects the colon or rectum. "The results indicated that QSOX2 gene expression was upregulated in multiple solid tumors, such as colorectal cancer, bladder cancer, breast cancer, clear cell renal cell cancer, esophageal cancer, stomach cancer, and others than in their matched adjacent NTTs." (PMID 34858968, 2021).
blastoma (1 paper, 2021). A malignant neoplasm composed of undifferentiated cells. "The QSOX2 gene encodes quiescin sulfhydryl oxidase 2, a member of the sulfhydryl oxidase/quiescin-6 (Q6) family (QSOX1), which are involved in the sensitization of neuro-blastoma cells for IFN-gamma (IFNG)-induced cell death." (PMID 34205581, 2021).
colon adenocarcinoma (1 paper, 2021). "Consistent with the analysis results of the UALCAN database, QSOX2 was also found to be upregulated in numerous human solid cancers according to the TIMER 2.0 online database, including COAD (colon adenocarcinoma) and READ (rectum adenocarcinoma)." (PMID 34858968, 2021).
esophageal squamous cell carcinoma (1 paper, 2025). Esophageal squamous cell carcinoma (ESCC) is a type of esophageal carcinoma (EC) that can affect any part of the esophagus, but is usually located in the upper or middle third. "Here, Quiescin Sulfhydryl Oxidase 2 (QSOX2) is identified, a protein involved in disulfide bond formation, is highly expressed in esophageal squamous cell carcinoma (ESCC), and is associated with poor patient prognosis." (PMID 40433832, 2025).
Infertility (1 paper, 2024). "However, we observed no apparent differences in the histology of the uterus between the wild-type and Qsox2-/- mice, which may indicate the potential contribution of the uterus to infertility." (PMID 38504307, 2024).
lymph node metastasis (1 paper, 2021). "Given that QSOX2 overexpression was positively associated with tumor diameter and lymph node metastasis, we wanted to detect whether QSOX2 facilitates the ability of proliferation and metastasis in CRC cells." (PMID 34858968, 2021).
tumor (6 papers, 2021 to 2026). "To explore the mechanism by which QSOX2 regulates tumor stemness, we analyzed its correlation with MsigDB hallmark gene sets using the TCGA database." (PMID 40433832, 2025). "QSOX2 upregulation in an unfavorable prognosis can probably be associated with the passage of cells in the S- and G2-phases of the cell cycle instead of apoptosis, and, as a consequence, with tumor development." (PMID 36232996, 2022). "Western blot and immunohistochemistry (IHC) staining confirmed the increased QSOX2 protein levels in clinical ESCC samples compared to paired non‐tumor esophageal tissues." (PMID 40433832, 2025). "In the present study, we found that overexpression of QSOX2 enhanced tumor stemness and chemoresistance, contributing to poor prognosis in ESCC." (PMID 40433832, 2025). "In contrast, QSOX2 silence via shRNA significantly suppressed tumor sphere formation in vitro and reduced tumor initiation frequency in vivo." (PMID 40433832, 2025). "Significant differences in QSOX2 protein expression were found between the NSCLC and adjacent tissue samples, and overexpression of QSOX2 was observed in the tumor tissue samples." (PMID 34350181, 2021). "Elevated expression of QSOX2 was correlated with lymph node metastasis and an advanced tumor-node-metastasis (TNM) stage in NSCLC." (PMID 34350181, 2021). "Quiescent sulfhydryl oxidase 2 (QSOX2), linked to poor outcomes in various cancers, remains poorly studied in LUAD, with its role in tumor progression mechanisms largely unknown." (PMID 41922310, 2026). "QSOX2 is often found to be highly expressed at the edge of tumor nests, suggesting that the microenvironment may regulate QSOX2 expression." (PMID 40433832, 2025). "In contrast, knockdown of QSOX2 in KYSE180 cells suppressed tumor growth." (PMID 40433832, 2025). "Furthermore, QSOX2 expression was higher in metastatic lymph nodes than in the primary tumor." (PMID 40433832, 2025). "Whether the expression of QSOX2 plays a regulatory role in tumor growth should be further studied." (PMID 34350181, 2021). "Therefore, increased QSOX2 may promote ESCC progression by regulating tumor stemness." (PMID 40433832, 2025). "To elucidate the expression of the QSOX2 gene in NSCLC and its impacts on survival and clinicopathological features, we extracted mRNA from the resected tumor tissue samples from 22 patients in cohort 1 with NSCLC and then analyzed by qPCR." (PMID 34350181, 2021). "However, whether QSOX2 is abnormally expressed in non-small cell lung cancer (NSCLC) and its role in tumor growth remains unclear." (PMID 34350181, 2021). "In this study, we showed that QSOX2, a secreted protein, was aberrantly expressed in NSCLC and periodically expressed in the cell cycle process of tumor cells, which implied that this protein might be a promising serum marker for the evaluation of tumor suppression after anticancer therapy." (PMID 34350181, 2021).
cancer (5 papers, 2021 to 2026). A tumor composed of atypical neoplastic, often pleomorphic cells that invade other tissues. "Intriguingly, cancer‐associated fibroblasts‐secreted IGF‐1 upregulates QSOX2 expression via IGF1R/Akt/mTOR/c‐Myc pathway, establishing a positive feedback loop that sustains ESCC cell stemness." (PMID 40433832, 2025). "QSOX2 is a relatively unstudied protein but is gaining attention because of its association with cancer." (PMID 38489772, 2024). "Furthermore, cancer‐associated fibroblasts (CAFs)‐activated IGF1R/Akt/mTOR/c‐Myc pathway transcriptionally upregulates QSOX2 expression, establishing a QSOX2/mTOR feedback loop that sustains ESCC cell stemness." (PMID 40433832, 2025). "First, we analyzed the expression of QSOX2 in various cancer types using the public gene expression data available through TCGA and CPTAC." (PMID 34858968, 2021). "According to UALCAN analysis, compared with the corresponding normal tissue, the mRNA expression of QSOX2 was significantly upregulated in most human cancers." (PMID 34858968, 2021). "Given that QSOX2 and QSOX1 have 40% identity in the primary amino acid structure and higher identity in the functional domain, reaching 68%, we suspected that QSOX2 might also participate in the tumorigenesis and progression of cancers." (PMID 34858968, 2021). "Since proteins in the ECM contains disulfide bonds, QSOX2, as an enzyme that generates disulfide bonds in substrate proteins, may also promote cancer cell growth, adherence, and invasion by regulating the ECM." (PMID 34858968, 2021). "Moreover, QSOX2 silencing in NSCLC cell lines resulted in inhibition of cancer cell proliferation, induction of apoptosis, and decreased expression of cell division-related genes (CENPF and NUSAP1) and Wnt pathway activators (PRRX2 and Nuc-β-catenin)." (PMID 34350181, 2021). "Furthermore, immunohistochemistry staining was performed to detect the expression of QSOX2, p21, and the cancer cell proliferation marker Ki67 in shQSOX2 and shCtrl groups." (PMID 34858968, 2021). "The results of bioinformatics analysis and clinical verification suggest that QSOX2 overexpression was closely related to the malignant progression of CRC patients, such as the ability of proliferation and metastasis, which is also an important feature of malignant tumors." (PMID 34858968, 2021). "However, to the best of our knowledge, the expression level and function of the QSOX2 gene in NSCLC and other malignant tumors have not been investigated." (PMID 34350181, 2021).
QSOX2 also shares sentences with these, for which no sentence is quoted: bladder cancer (1 paper); breast carcinoma (1); clear cell renal cell cancer (1); esophageal cancer (1); glioblastoma (1); non-small cell lung carcinoma (1); osteosarcoma (1); Pan (1); prostate carcinoma (1); rectum adenocarcinoma (1); stomach cancer (1).